IL15 (interleukin 15)
Description:
Cytokine that plays a major role in the development of inflammatory and protective immune responses to microbial invaders and parasites by modulating immune cells of both the innate and adaptive immune systems. Stimulates the proliferation of natural killer cells, T-cells and B-cells and promotes the secretion of several cytokines. In monocytes, induces the production of IL8 and monocyte chemotactic protein 1/CCL2, two chemokines that attract neutrophils and monocytes respectively to sites of infection. Unlike most cytokines, which are secreted in soluble form, IL15 is expressed in association with its high affinity IL15RA on the surface of IL15-producing cells and delivers signals to target cells that express IL2RB and IL2RG receptor subunits. Binding to its receptor triggers the phosphorylation of JAK1 and JAK3 and the recruitment and subsequent phosphorylation of signal transducer and activator of transcription-3/STAT3 and STAT5. In mast cells, induces the rapid tyrosine phosphorylation of STAT6 and thereby controls mast cell survival and release of cytokines such as IL4 (By similarity).
Synonyms: IL-15; MGC9721
Tractability: Antibody: a drug acting on it is in phase 2 or 3 trials; its Gene Ontology location is reachable by antibodies, with high confidence; UniProt places it where antibodies can reach, with medium confidence; UniProt predicts a signal peptide or a membrane-spanning region. PROTAC: a small molecule that binds it is known.
Target class: Secreted protein
Gene: Protein-coding gene on chromosome 4 (141,636,237 to 141,735,276, forward strand). Ensembl gene ENSG00000164136.
Subcellular location: Secreted (Isoform IL15-S48AA); Cytoplasm (Isoform IL15-S21AA); Nucleus
Subcellular location (Human Protein Atlas): Nuclear speckles; Nucleoplasm; Predicted to be secreted
Pathways (Reactome):
Immune System: Interleukin-15 signaling
Gene Ontology:
Molecular function: cytokine activity; protein binding; cytokine receptor binding
Biological process: interleukin-15-mediated signaling pathway; macrophage differentiation; neutrophil activation; positive regulation of interleukin-17 production; positive regulation of peptidyl-tyrosine phosphorylation; positive regulation of phagocytosis; tyrosine phosphorylation of STAT protein; cell surface receptor signaling pathway via JAK-STAT; cell-cell signaling; immune response; negative regulation of apoptotic process; negative regulation of cold-induced thermogenesis; positive regulation of cell population proliferation; positive regulation of cytokine production; positive regulation of immune response; positive regulation of inflammatory response; positive regulation of MAPK cascade; positive regulation of T cell proliferation; positive regulation of tissue remodeling; signal transduction; positive regulation of protein metabolic process
Cellular component: extracellular region; interleukin-15 receptor complex; nuclear speck; nucleoplasm; cytoplasm; endosome; Golgi apparatus; nucleus
Genetic constraint (gnomAD): Loss-of-function variants: 7 observed, 7.08 expected, observed/expected ratio (o/e) 0.99, 90% interval 0.56 to 1.74. That is too few expected variants to judge how well the gene tolerates losing a copy. Missense variants: 78 observed, 71.48 expected, observed/expected ratio (o/e) 1.09, 90% interval 0.91 to 1.32. Synonymous variants: 21 observed, 20.82 expected, observed/expected ratio (o/e) 1.01, 90% interval 0.71 to 1.45.
Homologues: Orthologues: chimpanzee IL15 (100% identical), macaque IL15 (94% identical), dog IL15 (84% identical), rabbit IL15 (83% identical), guinea pig IL15 (81% identical), pig IL15 (80% identical), mouse Il15 (73% identical), rat Il15 (72% identical), zebrafish il15 (26% identical), zebrafish il15l (16% identical).
Diseases named in the same sentence as IL15 in open-access papers:
IL15 is named in the same sentence as 526 diseases in open-access papers, as found by Europe PMC text mining. Sharing a sentence is not in itself a finding about the gene and the disease. The quoted sentences say what the papers report.
COVID-19 (148 papers, 2020 to 2026). A disease caused by infection with severe acute respiratory syndrome coronavirus 2. "The elevation of IL-5, IL-6, and IL-15 in PLWH/COVID-19 mirrors previously reported cytokine signatures associated with hyperinflammation and adverse clinical outcomes in both infections." (PMID 41516165, 2025). "We identified IL-7, IL-15, and lymphotoxin-α as central mediators underlying severe COVID-19, related respiratory failure, and high-risk immune signatures." (PMID 38368384, 2024). "Consistent with prior reports, IL-6, well-known to associate with poor survival during COVID-19, IL-27, and IL-15 were also observed to stratify survival, but IL-6 displayed a lower hazard ratio than IL-18." (PMID 36894537, 2023). "Vector analysis conducted in the 1st trimester indicated that CXCL8, CCL3, CCL5, IL-1β, TNF-α, IL-12, IL-15, IL-1Ra, IL-10, and G-CSF were associated with convalescent COVID-19 in pregnant women." (PMID 37122732, 2023). "In previous studies, increased TNF-α, IL-1Ra, IL-6, IL-8, IL-15 and IL-10 serum levels were associated with higher mortality in COVID-19." (PMID 37969879, 2023). "Perhaps unexpectedly, several cytokines associated with severe COVID-19 and damaging cytokine overproduction (IL-6, IL-15, and IL-18) were reduced following coinfection at 5 d pvi." (PMID 35634338, 2022). "The analysis revealed that patients with high levels of resistin and IL-15 were at a high risk of suffering more severe COVID-19 symptoms; in concrete, they would more probably require invasive ventilation." (PMID 35330391, 2022). "Recently, CAR NK cells, engineered to express soluble IL-15 to promote their survival, have shown promising results in COVID-19 therapy, underlining the potential of IL-15 as viable treatment option." (PMID 36430566, 2022). "For this reason, we suggest the use of the IL-15-to-albumin ratio with cut-off point >105.4 to triage COVID-19 patients with increased mortality risk, which becomes more relevant in countries with slow vaccination rates." (PMID 34683480, 2021). "Among these molecules, IL-6 and IL-15 were the major contributors to the fatality risk in patients with severe COVID-19." (PMID 34829906, 2021). "In our analysis we observed that several biomarkers, including GM-CSF, MCP-1, MIP1α, TNFα, IL-1RA, IL-6, IL-8, IL-15 and IL-10 were associated with fatal outcomes in COVID-19." (PMID 34539631, 2021). "We demonstrate that systemic levels of IL15 track disease severity among patients and that the levels are notably elevated in the aged male (the predisposed age group in COVID-19, as per reports worldwide)." (PMID 34127431, 2021). "In line with previous evidence, we now report for the first time that combining IL-15 with albumin in a single prognostic ratio considerably improved our ability to identify COVID-19 patients at a much higher mortality risk." (PMID 34683480, 2021). "In this sense, we show that combining laboratory markers’ values with serum cytokines is an excellent strategy to improve the early recognition of COVID-19 patients with an increased risk of death, mainly albumin and IL-15." (PMID 34683480, 2021). "In these studies, critical COVID-19 outcomes, extended hospitalization and lymphopenia in COVID-19 patients, and poor prognosis and disease severity were associated with a significant increase in IL-2 cytokine family profile, including IL-2, IL-4, and IL-15." (PMID 37649897, 2023). "We identified key cytokines that were consistently associated with severity, like IL-10, an enhancer of NK cytotoxicity, and IL-15, a stimulator of NK cells, Obviously, the modeling methodology can be used to identify key players and predict outcome in new variants of COVID-19." (PMID 35529862, 2022). "In this sense, other cytokines and chemokines such as MCP-1, IL-10, IL-15, CXCL10, and CCL2 have been associated with SARS-CoV-2 viremia." (PMID 35783606, 2022).
COVID-19 (continued). "Since IL-15 also promotes activation and recruitment of neutrophils to site of inflammation, CD24Fc may suppress COVID-19-associated neutrophil activation and neutrophilia." (PMID 35012610, 2022). "Nevertheless, the combined use of IL-15 values with albumin to predict mortality in COVID-19 is unexplored, even though hypoalbuminemia is a common laboratory finding in patients with severe illness, and IL-15 belongs to the cytokine storm that is frequently associated with disease lethality." (PMID 34683480, 2021). "Thus, increased IL-15 levels and the associations of IL-15 with other clinical parameters could represent its signature in patients with severe COVID-19." (PMID 36012146, 2022). "However, when stratified according to sex, levels of 25(OH)D showed a significant positive correlation with EFG (R = 0.39, p < 0.05) and IL-15 (R = 0.39, p < 0.05), and a borderline significant association with IFNγ (R = 0.33, p = 0.06) in male patients with COVID-19." (PMID 36554094, 2022). "However, emerging evidence suggests that combining laboratory parameters with markers significantly involved in the cytokine storm may also help to predict the mortality risk in COVID-19 patients, mainly albumin and interleukin (IL)-15." (PMID 34683480, 2021). "Remarkably, patients with severe COVID-19 maintained significantly higher systemic IP-10, IL-1RA, IL-10, IL-15, and MIP-1β levels and mucosal IL-1RA, IL-12p40, and fractalkine through recovery and convalescence." (PMID 41313205, 2026). "IL-15 can promote TNF-α release in macrophages, which induces endothelial apoptosis, vascular permeability, and capillary leak syndrome—all implicated in COVID-19 progression." (PMID 40649865, 2025). "Concerning systemic immunity in COVID-19, clinical studies have shown a significant rise in pro-inflammatory cytokines and chemokines (IL-1β, IL-2, IL-6, IL-8, IL-15, IFN-γ, TNF, MCP-1), characterizing cytokine release syndrome (CRS) or cytokine storm." (PMID 40572294, 2025). "These cellular changes were accompanied by a sustained increase in serum IL-7 and IL-15 levels in patients after severe COVID-19 up to 6 months after acute infection." (PMID 41310351, 2025). "A number of cytokines signal through the JAK-STAT pathway, including IL-6, IL-2, IL-15, and IL-10, which are elevated in patients with COVID-19." (PMID 39599762, 2024). "In the CoVonly group receiving only the third booster dose of COVID-19 vaccine, we found, on 1 day (d1) post-immunization, a strong increase of the cytokines IL-15, IL-6, TNF-α and IFN-γ as well as of the chemokine CXCL10." (PMID 39340080, 2024). "At <6 DPOS, a model with FLT3, IL-17, IL-6, IL-15 emerged as the minimal cytokine set that explained 62% of variability in COVID-19 hospitalization (Akaike information criterion or AIC = 41.4; n = 49)." (PMID 39650666, 2024). "The newly reported genetic variant of ACE2 showed a positive correlation with CD40L, IL-1β, IL-2, IL-15, and IL-17A in COVID-19 patients." (PMID 38855114, 2024). "In the same study, changes in INF-r and IL-15 levels were confirmed to be positively correlated with COVID-19 vaccine-induced antibody titers, and the authors suggested that this indicated the development of an effective humoral response after vaccination." (PMID 37049424, 2023). "al. who find IP-10, IL-2, MDC, IL-15 significant at the univariate level for discriminating MIS-C from COVID-19." (PMID 37685502, 2023). "Probiotics also have an immunomodulating role in the cytokine storm (IL-1B, IL-6, IL-15, IL-15, IL-17 IFN-g, TNF-a), and it can thus be deduced that probiotics are involved in fighting the cytokine storm associated with COVID-19." (PMID 37049576, 2023). "This study also demonstrates that IL-15 levels are higher in blood and lung tissues from COVID-19 patients." (PMID 36894537, 2023). "Rizo-Tellez reported the IL-15/albumin ratio as a predictor of mortality with a cut-off value > 105.4 in hospitalized COVID-19 cases." (PMID 38006008, 2023).
COVID-19 (continued). "It has also been reported that NK cell-activating cytokines such as IL-12, IL-15 and IL-21 are reduced in individuals with COVID-19." (PMID 36936055, 2023). "In agreement, Liu and colleagues demonstrated that IL-15 plays a role in NK cell dysfunction observed in most severe COVID-19 patients." (PMID 35844604, 2022). "An extensive search of the literature concerning IL-15 in COVID-19 development showed little data; however, we found that IL-15 is one of the first cytokines to increase its concentration in response to mRNA vaccination." (PMID 36430621, 2022). "Among the cytokines analyzed, those that correlated with a worse prognosis of COVID-19 were resistin, IL-6, IL-8, IL-15, MCP-1 and TNF-α." (PMID 35330391, 2022). "Currently, a study revealed that MIS-C and KD shared same fundamental nature of the host immune response continuum as COVID-19 which was found to be predominantly IL15/IL15RA-centric cytokine storm." (PMID 36159873, 2022). "The positive correlation between the P2X7 receptor and CRP increased in the moderate and severe COVID-19 groups, but in contrast, the positive IL-6 and IL-15 correlation with CRP decreased in these groups." (PMID 35663992, 2022). "Among patients with solid tumors, the analysis also showed a trend to increased concentrations of IL-15 in plasma of patients that recovered from the disease compared with patients who only presented mild COVID-19." (PMID 36700209, 2022). "A positive correlation was found between COVID-19 BAL fluid levels of IL-15 and CXCL10 or CCL2, cytokines/chemokines involved in monocyte, lymphocyte, and NK cell functions." (PMID 34793331, 2022). "The most relevant results are that resistin, IL-6, IL-8, IL-15, IL-18, MCP-1 and TNF-α are the main cytokines associated to COVID-19 symptomatology; meanwhile resistin, IL-8, IL-15, MCP-1 and TNF-α used to be associated with oxygen therapy necessity." (PMID 35330391, 2022). "In the present study, we corroborate in a cohort of COVID-19 patients from the southeast of Spain an elevated concentration of the cytokines IL-6, IL-15, IL-18 and IL-1RA." (PMID 35663992, 2022). "COVID-19 patients showed higher levels of pro-inflammatory cytokines, such as IP-10 IL-15,IL-1RA NT-proBNP, and the angiogenic growth factor HGF, among others." (PMID 35844615, 2022). "Nevertheless, we found markedly lower levels of IFNG-induced chemokine CXCL10 in KD and CXCL9 and IL15 in both KD and severe COVID-19, suggesting blunted type II interferon signaling in both KD and severe COVID-19 conditions." (PMID 36159873, 2022). "The inflammation of the olfactory epithelium in COVID-19 seems to be supported by the release of cytokines such as IL-1, IL-6, IL-12, IL-15, and TNF-α, and by activating lymphocytes and macrophages, initiating the so-called “cytokine storm”." (PMID 35269410, 2022). "Increases in IL-12p40, IL-12p70, IL-15 and IL-27 in severe COVID-19 patients have previously been described." (PMID 36142255, 2022). "Regarding the prediction of the COVID-19 outcome, using different methods, we found that IL-15 and resistin were the best predictors of the requirement of invasive ventilation." (PMID 35330391, 2022). "Hematologic cancer patients that showed highly networked and coordinated anti-SARS-CoV-2 antibody production, with central importance of IL-4, IL-5, IL-12A, IL-15, and IL-17A, presented only mild COVID-19." (PMID 36700209, 2022). "To determine how gene expression varies based on normalization with CypA and GAPDH, we looked at genes such as NRF2, IL-6, and IL-15, whose expression profiles based on RNA sequencing were previously reported in COVID-19 patients (30, –, 33)." (PMID 36377893, 2022). "The mechanisms through which IL-15 and albumin contribute to mortality in COVID-19 remain to be elucidated." (PMID 34683480, 2021).
COVID-19 (continued). "In fact, IL15 is part of an immune-based biomarker signature associated with mortality in COVID-19 patients, and CCL4 has been shown to be elevated in COVID-19 patients who eventually died due to the disease." (PMID 34071557, 2021). "Both IL-18 and IL-15 were reported as potential factors contributing to respiratory demise in COVID-19 patients." (PMID 34177897, 2021). "Other cytokines similarly increased in patients with severe pandemic influenza A(H1N1) and COVID-19 included IL-7, IL-15, IL8, and CXCL10." (PMID 33995342, 2021). "IL-4, IL-7, IL-8, IL-12p70, IL-15, and VEGF were also associated with increased risk of intubation in COVID-19 subjects." (PMID 33995342, 2021). "A recent study showed that IL-15 serum levels increase in the same proportion as COVID-19 mortality." (PMID 34683480, 2021). "Conversely, a combination between the values of IL-15 and albumin significantly improved the ability to predict mortality in COVID-19 patients." (PMID 34683480, 2021). "As we outlined here, this is the first study showing that combining IL-15 serum values with albumin improves mortality prediction in COVID-19 patients." (PMID 34683480, 2021). "As we have shown here, the IL-15-to-albumin ratio can predict mortality in COVID-19 patients with an AUROC of 0.841, which improves the predictive accuracy of NAR, BAR, and CAR." (PMID 34683480, 2021). "A recent cross-sectional study showed that COVID-19 patients with increased serum levels of IL-15 at admission experience a longer duration of hospitalization." (PMID 34683480, 2021). "As we have outlined here, as far as we know, this is the first study demonstrating that the combined use of the IL-15-to-albumin ratio improves mortality prediction in COVID-19 patients that meet hospitalization criteria." (PMID 34683480, 2021). "Other cytokines like IL-15 and IP-10 presented significantly increased levels in COVID-19 compared to healthy donors (p < 0.001, in both cases)." (PMID 33718270, 2021). "COVID-19 patients showed a profile of pro-inflammatory serum cytokines compared to controls, with higher levels of IL-2, IL-6, IL-15, and IP-10." (PMID 33718270, 2021). "However, IL12RB1 and IL12RB2 transcript levels as well as those encoding for the cytokines, IL15 and IL12 (IL15 and IL12A, respectively) decreased in life-threatening COVID-19 and MIS-C." (PMID 41285788, 2025). "In PLWH/COVID-19, elevated IL-6, IL-5, IL-9, and IL-15 interleukins compared to COVID-19-only could induce a strong immune response in these patients." (PMID 41516165, 2025). "Also, in PLWH/COVID-19, serum levels of a different set of interleukins (IL-5, IL-6, IL-9, and IL-15) and chemokine CXCL10 were upregulated." (PMID 41516165, 2025). "The high level of IL-6 and IL-15 in PLWH/COVID-19 compared to COVID-19-only may produce an synergistic effect of pre-existing HIV-related immune activation and the acute immune response induced by SARS-CoV-2." (PMID 41516165, 2025). "In line with this hypothesis, human data show that plasma 25(OH)D3 levels are positively correlated with plasma IL-15 levels in tuberculosis-infected patients and also in men infected with COVID-19." (PMID 40134939, 2025). "The IL-15-to-albumin ratio enhanced mortality prediction in hospitalized COVID-19 patients." (PMID 40649865, 2025). "The cytokines whose excessive expression may predict a worse prognosis of COVID-19 patients also include IL-12 and IL-15." (PMID 39335569, 2024). "Comprehensive single-cell analyses across the COVID-19 severity spectrum have also revealed increased quantities of circulating plasma cells/plasmablasts and IL-15-related exhaustion of circulating NK cells in severe COVID-19, findings consistent with those observed in our cohort." (PMID 38368384, 2024). "Interestingly, the genetic variant chrX:15,584,534_ of the ACE2 gene correlated positively with CD40L, IL-1β, IL-2, IL-15, and IL-17A in COVID-19 patients." (PMID 38855114, 2024).